CXCR4 (C-X-C motif chemokine receptor 4)
Diseases named in the same sentence as CXCR4 in open-access papers (continued):
Sharing a sentence is not in itself a finding about the gene and the disease.
melanoma (continued). "The expression of RUNX2, MMP13 and CXCR4 at the protein level was also verified in the same melanoma cell lines." (PMID 38474372, 2024). "CXCR4 is commonly found to be highly expressed in hematologic malignancies and many types of solid tumors, including melanoma, and tumors of the lung, breast and ovary." (PMID 38972952, 2024). "In this study, we aimed to investigate the role of RUNX2 and CXCR4 in melanoma, using in vitro cell cultures." (PMID 38474372, 2024). "In the present work, we succeeded in demonstrating the involvement of RUNX2 and CXCR4 in multiple stages of the pathophysiology of melanoma progression and metastasis." (PMID 38474372, 2024). "We modulated the levels of RUNX2 in melanoma cells and assessed its effects on CXCR4 as well as on markers of cell invasion and autophagy." (PMID 38474372, 2024). "CXCL12 is ubiquitously expressed in many tissues, and a distribution of CXCL12 similar to that of CXCR4 has been observed in melanoma cells." (PMID 38474372, 2024). "Our previous study suggested that T22 exhibited dual functionality by targeting CXCR4 and facilitating cargo release within the cells in melanoma." (PMID 39559553, 2024). "IHC staining of melanoma liver metastases and colorectal cancer liver metastases showed CXCR4 cytomembrane and cytoplasm staining pattern, while normal hepatocytes showed absent or weak staining." (PMID 38524630, 2024). "Previous studies showed that the CXCL12/CXCR4 axis contributed to the formation of a pre‐metastatic niche for metastatic melanoma cells and metastasis development." (PMID 39496484, 2024). "In conclusion, our study highlights the significant role of CXCR4 in driving the transformation of melanoma cells." (PMID 38474372, 2024). "In the resulting premetastatic niche consisting of VEGFR1+ progenitors, fibroblasts and fibronectin, expression of CXCL12 became highly expressed leading to the homing of CXCR4+ melanoma cells and metastasis." (PMID 37173970, 2023). "CXCR4 is the most abundantly expressed chemokine receptor in more than 23 human cancers, including breast, ovarian, melanoma, prostate, and colorectal cancer, while being expressed at low or undetectable levels in numerous normal tissues." (PMID 37629071, 2023). "The role of the chemokine receptor, CXCR4 is highlighted in cancer, due to its ubiquitous expression by various cancers, including melanoma." (PMID 37170733, 2023). "The major chemokine/chemokine receptor interactions occurring in melanoma development and progression include the CXCR4/CXCR7/CXCL12, CXCR3/CXCL9,10,11, CXCR1,2/CXCL8, CCR2/CCL2, CCR4/CCL17,22, CCR5/CCL5, CCR7/CCL21 and CCR10/CCL27 axes." (PMID 37170733, 2023). "Inhibition of these transcription factors slows melanoma cell growth, migration, and motility, as well as reduces CXCR4 expression." (PMID 38070141, 2023). "Mechanistically, FTO overexpression promoted melanoma development by increasing the key oncogenic genes (PD-1, CXCR4 and SOX10) in mRNA and protein levels and SOX10, and inhibiting IFN-γ-induced melanoma cell death." (PMID 37264402, 2023). "For instance, mavorixafor, an orally bioavailable CXCR4 antagonist, has shown promise in modulating immune cell trafficking in melanoma patients." (PMID 38129870, 2023). "Both treatments, singly or combined, increased expression of CCR7 and CXCR4 in melanoma cell lines, which, despite resulting in inhibition of cell growth, led to enhanced migration towards ligands." (PMID 35203305, 2022). "Lymphatic endothelial cells stimulate the migration of CXCR4+/CD133+ melanoma cells toward lymphatic vessels, and blocking CXCR4 signaling inhibits this metastasis." (PMID 36158182, 2022). "High concentrations of CXCL12, the ligand of CXCR4, are produced in the lungs and injected CXCR4-expressing B16 melanoma cells are able to efficiently colonize the lung." (PMID 35158973, 2022). "Expression of CXCR4, CCR7 and CCR10 on the surface of melanoma cells is associated with a poor prognosis." (PMID 35158973, 2022).
melanoma (continued). "Direct expression of one or both factors has been observed in a wide range of tumors, and expression of CXCR4/CXCL12 has been associated with a poor prognosis in multiple cancers, including breast, ovarian, renal, lung, and melanoma." (PMID 36923305, 2022). "CXCR4 enhances the proliferation and survival of melanoma cells by increasing the number of tumour blood vessels." (PMID 36140541, 2022). "The Cancer Genome Atlas (TCGA) mRNA data analysis of tumor resections from patients with advanced melanoma indicated higher CXCR4 pretreatment expression in patients responding compared with those not responding to treatment." (PMID 35552271, 2022). "In vivo CXCR4 overexpression in melanoma has been reported and has been found to be higher in metastasis than primary tumours, and, in addition, it is associated with a higher tumour stage." (PMID 36140541, 2022). "CC chemokine receptor 7 (CCR7) and CXC chemokine receptor 4 (CXCR4) are epigenetically upregulated in melanoma cells, and have the ability to induce metastasis of melanoma." (PMID 34198989, 2021). "Omega-6 fatty acids induce CXCR4 expression in melanoma, although ω3 fatty acids decrease CXCR4 expression, leading to the prevention of melanoma metastasis." (PMID 34069297, 2021). "m6A-YTHDF2 inactivity contributes to melanoma progression by enhancing the expression and stability of key immune checkpoint factors, including PD-1, CXCR4, and SOX1040." (PMID 34016959, 2021). "Of note, the ablation of CXCR4+ myeloid population was reported to suppress melanoma and glioblastoma growth in pre-clinical models, which implies that Mφ2 is an immunosuppressive population induced by neo-aPD1." (PMID 34836966, 2021). "FTO expression is regulated by autophagy pathway and nuclear factor kappa B pathways and can be induced by metabolic stress; the FTO protein itself regulates the expression of known melanoma-related genes encoding PD-1 (PDCD1), CXCR4, and SOX10." (PMID 34105069, 2021). "Activation of chemokine receptor CXCR4/CXCL12 signaling is also involved in TAMs recruitment of melanoma." (PMID 33224886, 2020). "In murine models of leukemia, melanoma and ovarian cancer, CXCR4 inhibition, obtained with blocking antibodies or with the CXCR4 antagonist AMD3100, increased the effector to Tregs ratio at the tumor site and reduced tumor growth." (PMID 33013822, 2020). "Our data correlated the osteotropism of melanoma cells to the activation of the SDF-1/CXCR4/CXCR7 axis following the exposition of tumor cells to bone-derived soluble factors." (PMID 31324252, 2019). "Third, we used m6A- seq in combinaton with RNA-seq to identify more than 1000 potential transcriptome-wide m6A-modifiedgene targets for FTO, including the melanoma-promoting genes CXCR4 and SOX10." (PMID 31239444, 2019). "The CXCL12-loaded gel (CLG) attracted circulating CXCR4 positive melanoma cells diverting them from secondary sites." (PMID 31332163, 2019). "Targeting PD-1 and CXCR4 on PES43 melanoma cells reduced cell growth and inhibited survival signaling (pERK/pAkt) strengthen the effect of nivolumab that impaired pERK/pAkt and p4EBP1." (PMID 31661001, 2019). "In athymic mice, double targeting of CXCR4 and PD-1 significantly reduced human melanoma tumor growth as T cells independent effect." (PMID 31661001, 2019). "Numerous reports have previously suggested that CXCR4 is over-expressed in a variety of tumors including gastric, ovarian, pancreatic, melanoma, renal, cervical, colon, and hematological malignancies." (PMID 30564115, 2018). "Specifically, studies have shown that the ectopic expression of the chemokine receptor CCR7 in murine melanoma cells increases tumor-lymph node and -brain tissue homing in vivo, whilst CXCR4 promotes melanoma-lung tropism." (PMID 30460237, 2018). "X4P-001 is an oral, selective, allosteric inhibitor of CXCR4 that robustly inhibits the growth of murine B16-OVA melanoma." (PMID 30400835, 2018).
melanoma (continued). "In melanoma, CXCR4 inhibition with AMD11070 abrogated tumor cell migration in response to CXCL12 stimulation." (PMID 30420855, 2018). "In our melanoma model, elevated expression of CXCR4 upon MK2 deletion correlated with an accumulation of DCs in dLNs." (PMID 28924177, 2017). "CXCR-4 over-expressed on human melanoma cells has also been shown to play a role in melanoma progression." (PMID 28567163, 2017). "For example, promoters of melanoma biomarkers such as Cox-2, CXCR-4, tyrosinase and survivin have been incorporated into the viral genomes, which result in significantly enhanced oncospecificity." (PMID 28567163, 2017). "TGFβ induced an EMT-like effect on the activation of the PDGF signaling pathway and the subsequent activation of PI3K in human melanoma cells, and CXCR4 signaling induced EMT by the PI3K/AKT and ERK pathways in glioblastoma." (PMID 28415580, 2017). "Consistent with this, we found that the pro-inflammatory cytokines S100A8 and S100A9, as well as the chemokine receptor CXCR4, were highly and significantly upregulated in primary melanomas compared to benign nevi." (PMID 26918341, 2016). "AMD3100 was administered to melanoma-bearing mice peritumorally to directly evaluate the possible involvement of the CXCL12/CXCR4 pathway in A2BR-mediated effects within tumor environment, minimizing possible systemic effects of this molecule." (PMID 27590504, 2016). "The C-C chemokine receptor type 7 (CCR7) promotes melanoma cell metastasis to the C-C motif ligand 21 (CCL21)-rich lymph nodes while the C-X-C chemokine receptor type 4 (CXCR4)/C-X-C motif chemokine ligand 12 (CXCL12) axis facilitates pulmonary metastasis." (PMID 27598148, 2016). "These agonists produce robust calcium mobilization in human melanoma cell lines which can be blocked by the CXCR4-selective antagonist AMD3100." (PMID 27456816, 2016). "The importance of S100A proteins in melanoma development has been less studied, but the expression of CXCR4 has been reported to predict poor prognosis in melanoma." (PMID 26918341, 2016). "CXCR4 is important for the prognosis of several tumor types, including melanoma, colon, pancreatic, gastric cancer and STS." (PMID 25613038, 2015). "CXCR4 is the most common chemokine receptor in solid human cancers, including breast, melanoma, renal cell, brain, thyroid, non-small cell lung, pancreatic, ovarian, prostate, and colorectal cancers." (PMID 26318034, 2015). "The CXCR4+ population was enriched for small cells, reportedly a typical morphological feature for melanoma cells with CSC phenotype." (PMID 26110809, 2015). "Others showed that the de novo expression of CXCR4 is sufficient for metastasis to occur, shown by the B16 melanoma cell line transfected with CXCR4." (PMID 25254213, 2014). "5×105 B16 melanoma cells transduced with CXCR4 were pre-treated with peptides R, I or S (10 μM) or AMD3100 (10 μM) and inoculated into the tail vein of C57/BL mice." (PMID 24058588, 2013). "The murine B16 melanoma cell line experiences marked increase in metastasis to the lung when transfected with CXCR4." (PMID 24259307, 2013). "Involvement of PAX3 in melanoma migration is further supported by evidence showing that other genes associated with cell migration, including MCAM, CSPG4, and CXCR4, are targeted by PAX3, as shown by ChIP assay in A2058 melanoma cells." (PMID 24069584, 2013). "Experimental models of melanoma, colon, pancreatic, thyroid, and prostate cancer have demonstrated that organ directed metastasis is mediated by CXCR4+ tumor cells migrating to CXCL12+ organs such as the liver and the lungs." (PMID 23847541, 2013). "They showed that PAX3 promoted a less differentiated, stem-like (via HES1, SOX9, NES, DCT), motile (via MCAM, CSPG4, and CXCR4) phenotype, characteristic of melanomas with high metastatic potential." (PMID 24069584, 2013).
melanoma (continued). "CXCR4 is highly expressed in solid human cancers, including breast, malignant melanoma, brain, anaplastic thyroid, non-small cell lung, pancreatic, ovarian, prostate, and colorectal." (PMID 25285238, 2013). "In vitro experiments have shown that the directional migration of a range of cancer cells (e.g., ovarian, pancreatic, rhabdomyosarcoma and melanoma) is stimulated by the interaction between CXCR4 and CXCL12." (PMID 22272201, 2012). "It is also involved in tumor cell trafficking as CXCR4 overexpression is known in more than 20 human tumor types, including ovarian, prostate, esophageal, melanoma, neuroblastoma, and renal cell carcinoma." (PMID 23369485, 2012). "CXCR4 was required for the initial phases of melanoma cell chemotaxis and their arrival in the lungs, whereas MT1-MMP was necessary for subsequent invasion and dissemination of the tumor." (PMID 22496978, 2012). "Murine melanoma B16 cells (5 × 105) were injected into CXCR4+/+ and CXCR4+/− C57BL/6 and mice were treated for 10 days with 1.25 mg/kg of Plerixafor." (PMID 22399057, 2012). "Studies indicated that chemoresistant CD133+ melanoma cells were highly enriched with CXCR4 after chemotherapy thereby enhancing metastatic potential in vivo." (PMID 24212647, 2011). "The expression of SDF-1α, CXCR4 and endostatin, and effects of endostatin to cultured melanoma cells and lung metastases were also studied." (PMID 22015555, 2011). "CXCR4 is also the chemokine receptor most commonly expressed in tumor cells, with increased expression in melanoma, breast, ovarian, gastric, prostate, colorectal, and lung cancer." (PMID 21234386, 2011). "CXCR4 expression has been shown to be an independent clinical prognostic marker in primary cutaneous malignant melanomas." (PMID 24212647, 2011). "As previously demonstrated in pancreatic and melanoma cell lines, the expression of CXCR4 was restored in the MDA-MB-435 cells upon 5-aza-CdR treatment." (PMID 22220212, 2011). "In cancer, T140 efficacy to block CXCR4 has been reported in different tumor models in vivo and in vitro, including leukemia, breast and lung cancers, and malignant melanoma." (PMID 20049170, 2010). "Poly D,L-lactic acid (PLA) microcapsules containing a T140 analog, 4F-benzoyl-TE14011, was subcutaneously injected in experimental metastatic models of CXCR4-positive B16-BL6 melanoma cells." (PMID 19787093, 2008). "Based on this literature, another group explored the use of the T22-PE24-H6 nanotoxin to induce tumor-selective and gasdermin-mediated immunogenic cell death in CXCR4+ melanoma mouse models, achieving strong synergy when combined with an anti-PD-1 immune checkpoint inhibitor therapy." (PMID 40307933, 2025). "In addition to CAFs, ECM components, and previously discussed targets such as CXCR4, FAP, TGF-β, and MMPs, several other TME-associated molecules and pathways have emerged as relevant to melanoma progression and therapy resistance." (PMID 40649909, 2025). "These include validated melanoma targets, such as CXCR4, MET and TYRP1." (PMID 40428399, 2025). "Similarly, doxorubicin encapsulating liposomes, decorated with the CXCR4 antagonist cyclic peptide R, significantly reduced the effective doxorubicin dose and lung metastases in a mouse model of melanoma." (PMID 40307933, 2025). "Further, in melanoma cells, CXCR4 is expressed on fibroblasts and CD133+ melanoma subpopulations." (PMID 40649909, 2025). "CXCR4 antagonists also reduced melanoma lung metastasis in mice." (PMID 38675738, 2024). "In addition, CXCR4, a chemokine receptor, has been shown to play a significant role in the invasion and metastasis properties of melanoma." (PMID 38474372, 2024). "Furthermore, a combination of ICIs and CXCR4 inhibitors in melanoma was shown to increase the expression of CD8+ TILs and significantly reduce tumour growth." (PMID 39496484, 2024).
melanoma (continued). "In addition, a self-assembling nanotoxin that can be used to target CXCR4 expression activates melanoma pyroptosis through the caspase-3-GSDME pathway in melanoma." (PMID 38654314, 2024). "Therefore, the inhibition of CXCR4, or its cell signalling function, is a potential therapeutic strategy against melanoma." (PMID 38474372, 2024). "To evaluate RUNX2 association with CXCR4 in melanoma cells, we started by detecting the expression of these two markers and the matrix metalloproteinase 13 (MMP13) invasiveness marker in several melanoma cell lines." (PMID 38474372, 2024). "Interestingly, melanoma EVs were found to induce melanoma cell osteotropism by activating the SDF-1/CXCR4/CXCR7 axis, where CXCR7 is required by melanoma cells to promote their chemotaxis toward SDF-1 gradients." (PMID 37371036, 2023). "The C-X-C motif chemokine receptor 4 (CXCR4) is expressed in numerous tissues and is overexpressed in more than 23 different types of human cancers including kidney, lung, brain, prostate, breast, pancreas, ovarian, and melanomas." (PMID 37697316, 2023). "Knockdown of FTO elevated the m6A level in transcripts of several critical melanoma-promoting genes, including PD-1, C-X-C motif chemokine receptor 4 (CXCR4), and SOX10, then accelerated RNA decay mediated by YTHDF2, restoring IFN-γ response in vitro and sensitizing anti-PD-1 treatment in vivo." (PMID 36810281, 2023). "For example, the chemokine receptor CXCR4 is active in melanoma metastasis." (PMID 38070141, 2023). "The inhibitory effects of CTCE‐9908 and MAZ‐51 on VEGFR‐3 and CXCR4 protein expression show the potential to affect parameters of metastasis on melanoma cells by inhibiting cell–cell or cell‐ECM interactions by blocking downstream signalling molecules that impact on adhesion." (PMID 36398426, 2022). "The CXCR4, indicated by green fluorescence, was distributed mostly on the melanoma cells." (PMID 35145271, 2022). "In addition, FTO suppression increased the m6A methylation of critical pro-tumorigenic melanoma cell-intrinsic genes (programmed cell death-1, PD-1; C-X-C motif chemokine receptor 4, CXCR4; and sex-determining region Y-box 10, SOX10)." (PMID 35628623, 2022). "In addition, a commercially available dermal filler, hyaluronic acid (HA)-based gel, loaded with CXCL12 was able to recruit and trap CXCR4-expressing B16 melanoma cells injected into mice, consequently leading to a reduction in lung metastases." (PMID 35158973, 2022). "In addition, the overexpression of VEGF‐C upregulates chemokine receptor CXCR‐4 in tumours (melanoma)." (PMID 36398426, 2022). "Moreover, treatment with CXCR4 antagonists has demonstrated robust inhibition of murine B16-OVA melanoma growth, and enhanced survival has been reported in multiple mouse models when a CXCR4 antagonist is combined with a checkpoint inhibitor." (PMID 36923305, 2022). "Melanoma cells also express CXCR‐4, a chemokine receptor, with CXCL12 as a corresponding ligand." (PMID 36398426, 2022). "In a meta-analysis of 13 studies investigating the CXCR4 expression in the tumour samples of 656 patients with malignant melanoma, it was found that the high expression of CXCR4 is associated with ulceration, increased tumour thickness and lymph node metastasis." (PMID 36140541, 2022). "It is stated in literature that targeting melanoma by CXCR4 inhibition may be a good way to destroy the tumour cells and that CXCR4 regulates tumour immunity." (PMID 35758810, 2022). "Since melanoma cells express both the CXCR‐4 and VEGFR‐3 receptors, CXCR‐4 and VEGF may be regarded as quantifiable markers of tumour metastasis." (PMID 36398426, 2022). "Blocking CXCL12/CXCR4 using AMD3100 (a CXCR4 inhibitor) could improve the efficacy of anti-PD-1 in melanoma." (PMID 34911533, 2021).